LINC00641 (long independently transcribed non-coding RNA 641)
Diseases named in the same sentence as LINC00641 in open-access papers (continued):
Sharing a sentence is not in itself a finding about the gene and the disease.
renal cell carcinoma (4 papers, 2021 to 2023). "In conclusion, LINC00641, as a carcinogen of renal cell carcinoma, plays a role by targeting mir-340-5p through ceRNA mechanism, and can be used as a potential target for the treatment of renal cell carcinoma." (PMID 35155216, 2021). "Knockdown of LINC00641 in renal cell carcinoma cell line decreased cell proliferation, invasion and increased apoptosis." (PMID 35155216, 2021). "For instance, LINC00641, located on human chromosome 14q11.2, has been demonstrated to have unique functional features and clinical significance in various cancers, including cervical cancer, renal cell carcinoma, and colorectal carcinoma." (PMID 38066643, 2023). "Zhang analyzed 48 cases of renal cell carcinoma and found that the expression of LINC00641 was related to clinical T stage (P < 0.01) and metastasis (P < 0.05), and Kaplan-Meier survival analysis showed that the high LINC00641 expression group had poor prognosis (P < 0.05)." (PMID 35155216, 2021). "However, the detailed biological role of LINC00641 in renal cell carcinoma (RCC) remains largely unclear." (PMID 33853611, 2021). "For example, LINC00641 is involved in regulating the onset and progress of non-small-cell lung cancer, renal cell carcinoma, and gastric adenocarcinoma." (PMID 35756081, 2022).
cervical cancer (3 papers, 2021 to 2023). A primary or metastatic malignant neoplasm involving the cervix. "In general, LINC00641 is a tumor suppressor of cervical cancer and plays an important role in its occurrence and development." (PMID 35155216, 2021). "In cervical cancer cell lines, up-regulation of LINC00641 inhibits cell proliferation, increases apoptosis, reduces invasion and migration ability, and inhibits EMT." (PMID 35155216, 2021). "After further exploring the mechanism of LINC00641, combined with Starbase bioinformatic analysis and experiments, it was proved that miR-378a-3p was the target of LINC00641 and LINC00641 inhibited the growth of cervical cancer cells by reducing the expression of miR-378a-3p." (PMID 35155216, 2021). "Fish showed that LINC00641 was abundant in the cytoplasm of cervical cancer cells." (PMID 35155216, 2021). "LINC00641 deserves to be regarded as a new biomarker in the treatment of cervical cancer." (PMID 35155216, 2021). "In conclusion, LINC00641 can competitively bind miR-378a-3p through the ceRNA mechanism, so as to increase the expression of CPEB3 mRNA and inhibit the proliferation, migration and invasion of cervical cancer cells." (PMID 35155216, 2021).
colorectal carcinoma (3 papers, 2022 to 2023). A malignant epithelial neoplasm that arises from the colon or rectum and invades through the muscularis mucosa into the submucosa. "Nonetheless, the precise biological roles of LINC00641 in colorectal cancer (CRC) remain elusive." (PMID 35756081, 2022). "In addition, we explored the potential underlying mechanism to verify whether LINC00641 can upregulate GOLPH3 expression through sponging miR-450b-5p, ultimately exerting an oncogene function in colorectal cancer." (PMID 35756081, 2022).
gastric adenocarcinoma (3 papers, 2020 to 2021). "LINC00641 expression was associated with prognosis and oxaliplatin resistance in patients with gastric adenocarcinoma." (PMID 32917936, 2020). "In another study, the inhibition of linc00641 blocked cell proliferation and migration in gastric adenocarcinoma." (PMID 33714199, 2021). "To gain insight into the clinical value of LINC00641 in gastric adenocarcinoma, we examined the expression of LINC00641 in 173 gastric adenocarcinoma tissues." (PMID 32917936, 2020). "Linc00641 downregulation inhibits cell proliferation and migration in gastric adenocarcinoma." (PMID 33714199, 2021). "Furthermore, miR-582-5p was proved to be a downstream target of LINC00641 in gastric adenocarcinoma cells using Starbase V3.0." (PMID 32917936, 2020). "In addition, we found that up-regulation of LINC00641 in gastric adenocarcinoma promoted cell migration in vitro and induced autophagy initiation under L-OHP treatment." (PMID 32917936, 2020).
lung carcinoma (3 papers, 2020 to 2024). "In another aspect, low expression of LINC00641 caused a ferroptotic vulnerability in lung cancer cells, which may serve as a potential ferroptosis-related therapeutic target for lung cancer." (PMID 37311754, 2023). "Interestingly, knockdown of LINC00641 increased AA metabolism and boosted the susceptibility to ferroptosis inducers in lung cancer cells." (PMID 37311754, 2023). "We demonstrated that LINC00641 suppressed lung cancer by inhibiting migration and invasion in vitro and metastasis in vivo." (PMID 37311754, 2023). "In our study, we demonstrated low expression of LINC00641 was associated with poor outcomes in LUAD patients and knockdown of LINC00641 promoted tumorigenesis and metastasis of lung cancer." (PMID 37311754, 2023). "As a double-sided coin, low expression of LINC00641 also conveyed a ferroptotic vulnerability for lung cancer cells." (PMID 37311754, 2023). "GSEA using RNA-seq data revealed that LINC00641 negatively regulated the EMT process in lung cancer cells." (PMID 37311754, 2023). "The results showed that the LINC00641 expression in lung cancer cell lines was lower than that in HBE cell line." (PMID 37311754, 2023). "In this study, we revealed that knockdown of LINC00641 increased the HuR protein levels (mainly in cytoplasm) in lung cancer cells." (PMID 37311754, 2023). "Taken together, these results demonstrated that LINC00641 acted as a tumor suppressor in lung cancer partially through HuR." (PMID 37311754, 2023). "Our RNA-seq and mass spectrometry data also supported that knockdown of LINC00641 altered the ferroptosis pathway and ferroptosis related AA metabolism in lung cancer cells." (PMID 37311754, 2023). "Collectively, our in vivo and in vitro data supported LINC00641 as a tumor suppressor in lung cancer." (PMID 37311754, 2023). "To confirm this hypothesis, we first found a significant correlation between YTHDC1 and LINC00641 expression in lung cancer by using GEPIA database." (PMID 37311754, 2023). "LINC00641 was also involved in lung cancer by sponging miR-424-5p to upregulate PLSCR4." (PMID 37311754, 2023). "Taken together, these results demonstrated that lung cancer cells with low LINC00641 expression were more likely to undergo EMT, however, low LINC00641 expression could also cause a ferroptotic vulnerability for lung cancer treatment." (PMID 37311754, 2023). "Our study demonstrated that LINC00641 acted as a tumor suppressor by regulating EMT in lung cancer." (PMID 37311754, 2023). "Our results have shown that LINC00641 knockdown promoted EMT in the tumor cells, suggesting lung cancer patients with low LINC00641 expression might be likely to progress into a refractory cancer." (PMID 37311754, 2023). "LINC00641 has been involved in several cancers, however, its specific roles in lung cancer treatment remain largely unknown." (PMID 37311754, 2023). "Interestingly, low expression of LINC00641 coincidently conveyed a ferroptotic vulnerability in lung cancer." (PMID 37311754, 2023). "We next investigated the biological functions of LINC00641 in lung cancer." (PMID 37311754, 2023). "We next wanted to identify the molecular pathways by which LINC00641 suppressed lung cancer." (PMID 37311754, 2023). "Interestingly, LINC00641 knockdown in lung cancer cells increased the arachidonic acid metabolism and promoted ferroptosis sensitivity." (PMID 37311754, 2023). "In addition, the increased cytoplasmic HuR after LINC00641 knockdown suggested that LINC00641-knockdown could facilitate HuR protein translocation from nucleus to cytosol, which may provide potential strategies for targeting HuR in lung cancer treatment." (PMID 37311754, 2023). "LINC00641 expression levels were also assessed in a normal lung epithelial cell line (HBE) and three lung cancer cell lines (H1299, H1975 and A549)." (PMID 37311754, 2023). "The level of LINC00641 and H19 in lung cancer cell lines was found to be evidently lower than that in normal lung cell lines." (PMID 32869486, 2020).
lung adenocarcinoma (2 papers, 2023 to 2024). A carcinoma that arises from the lung and is characterized by the presence of malignant glandular epithelial cells. "Here, we reported that LINC00641 was down-regulated in tumor tissues and its downregulation was associated with poor outcomes in lung adenocarcinoma." (PMID 37311754, 2023).
prostate carcinoma (2 papers, 2021 to 2022). A carcinoma that arises from epithelial cells of the prostate gland. "In prostate cancer cell lines, over expression of LINC00641 inhibits cell proliferation, invasion and promotes apoptosis." (PMID 35155216, 2021). "When further exploring the mechanism of LINC00641 in prostate cancer, it was found that miR-365a-3p was a downstream target of LINC00641 and miR-365a-3p was up-regulated in prostate cancer and negatively correlated with LINC00641." (PMID 35155216, 2021). "Liu analyzed 23 prostate cancer patients and found that the low LINC00641 expression group had a lower survival rate than the high LINC00641 expression group (P < 0.05)." (PMID 35155216, 2021). "Overexpression of LINC00641 inhibited cell proliferation, invasion and promotes apoptosis in prostate cancer cell lines." (PMID 35155216, 2021). "In conclusion, LINC00641 can be used as a tumor suppressor of prostate cancer, which can increase the expression of VGLL4 and inhibit the proliferation and invasion of prostate cancer cells by competitively binding miR-365a-3p through the ceRNA mechanism." (PMID 35155216, 2021).
renal carcinoma (2 papers, 2021 to 2022). A carcinoma arising from the epithelium of the renal parenchyma or the renal pelvis. "In this study, the expression and biological function of LINC00641 were assessed in renal carcinoma both in vitro and in vivo." (PMID 33853611, 2021).
colon cancer (1 paper, 2022). "Herein, results indicated that LINC00641 contents were correlated with dismal prognosis in CRC, and LINC00641 silencing remarkably dampened growth and infiltration of colon cancer cells in vitro and in vivo." (PMID 35756081, 2022).
cutaneous squamous cell carcinoma (1 paper, 2021). "In cutaneous squamous cell carcinoma, LINC00641 overexpression decreased cell proliferation, migration and invasion ability in vitro, and the tumor volume of LINC00641 overexpression group was smaller in nude mouse tumorigenesis experiment." (PMID 35155216, 2021).
glioblastoma (1 paper, 2020). The most malignant astrocytic tumor (WHO grade IV). "One study reported that LINC00641 was associated with extracellular matrix receptor interaction, focal adhesion, and mitogen-activated protein kinase signaling pathways in glioblastoma according to the WGCNA (weighted gene co-expression network analysis) algorithm." (PMID 32917936, 2020).
kidney cancer (1 paper, 2021). Primary or metastatic malignant neoplasm involving the kidney. "Secondly, detailed investigation of genes that comprise the lncRNA LINC00641/miR-340-5p axis should also yield further insight into the mechanism by which lncRNA LINC00641 overexpression induces kidney cancer progression." (PMID 33853611, 2021).
lentivirus infection (1 paper, 2021). Virus diseases caused by the Lentivirus genus. "We observed that linc00641 expression was increased in the BGC-823 and MGC-803 cells after linc00641 lentivirus infection." (PMID 33714199, 2021).
papillary thyroid carcinoma (1 paper, 2024). "For instance, LINC00641 destabilized GLI1 mRNA through interacting with RPB IGF2BP1, thereby suppressing malignant traits of papillary thyroid carcinoma cells." (PMID 39425009, 2024).
rectal cancer (1 paper, 2021). A primary or metastatic malignant neoplasm that affects the rectum. "Xue’s study included 50 cases of rectal cancer and made a survival curve, and found that the high LINC00641 expression group had worse survival (P < 0.05)." (PMID 35155216, 2021). "When LINC00641 was knocked down, the proliferation and migration of rectal cancer cells decreased." (PMID 35155216, 2021). "LINC00641 plays a carcinogenic role in rectal cancer through miRNA-424-5p/PLSCR4 axis, which can provide a new target for the treatment of rectal cancer." (PMID 35155216, 2021).
tumor (15 papers, 2019 to 2023). "Clinical correlation analysis manifested higher LINC00641 level was associated with higher Enneking stage, larger tumor size, and positive distant metastasis in patients with OS (P < 0.05)." (PMID 35266447, 2022). "The lung metastases in mice were also monitored using micro-CT, which showed that lung metastasis displayed highly diffuse tumor morphology, spread throughout the lung in LINC00641 knockdown group compared to the control." (PMID 37311754, 2023). "Next, OS mice xenograft tumor model was established in vivo to further figure out the impact of LINC00641 deletion on tumor growth." (PMID 35266447, 2022). "As shown in, DDP therapy or declination of LINC00641 gave rise to a decrease in tumor volume and weight, which indicated that DDP therapy or silenced LINC00641 repressed the growth of OS tumor in vivo." (PMID 35266447, 2022). "In vivo experiments also proved that overexpression of LINC00641 inhibited tumor formation in nude mice." (PMID 35155216, 2021). "Linc00641 has been reported to play both an oncogenic role and a tumor suppressive function in different types of human cancers." (PMID 33714199, 2021). "Our findings identified LINC00641 as a tumor suppressor through inhibiting EMT." (PMID 37311754, 2023). "The promoting effect of LINC00641 knockdown on EMT indicated that LINC00641 may function as a tumor suppressor by regulating EMT." (PMID 37311754, 2023). "Xenografted tumor model in vivo was utilized to determine the function of LINC00641." (PMID 35266447, 2022). "Notably, the proliferative and migratory abilities of HCT-116 and SW480 cells were significantly inhibited by the knockdown of LINC00641 both in vitro and in vivo, illustrating that LINC00641 exerted a tumor-promotion role in CRC." (PMID 35756081, 2022). "In addition, the efficient knockdown of LINC00641 significantly slowed tumor growth (P < 0.01) and decreased tumor weight (P < 0.01) compared with SCR group." (PMID 33853611, 2021). "Linc00641 has also exhibited a tumor promotion function in some human cancers." (PMID 33714199, 2021). "Moreover, the expression of LINC00641 and miR-340-5p were detected in xenograft tumor and LINC00641 was decreased (P < 0.01), while miR-340-5p expression was increased due to LINC00641 upregulation." (PMID 33853611, 2021). "Therefore, LINC00641 can change the sensitivity of tumor to drugs by regulating the biological behavior of tumor cell proliferation and invasion, and it is a promising target for cancer treatment." (PMID 35155216, 2021). "In vivo, LINC00641 overexpression significantly inhibited tumor volume." (PMID 35155216, 2021). "Therefore, LINC00641 shows pivotal effects in the promotion of tumor in CRC." (PMID 35756081, 2022). "Deletion of LINC00641 inhibited the proliferation and invasion of RCC cells as well as tumor growth in vivo." (PMID 33853611, 2021). "LINC00900, MIR210HG, MIR22HG, PVT1, and SNHG18 expression increased, whereas HAR1A, LINC00641, SLC25A21-AS1, and SNAI3-AS1 expression decreased with tumor grade." (PMID 34288803, 2021). "The expression of LINC00641 was overexpressed in RCC tissues and cell lines, and high LINC00641 expression was correlated with tumor-node-metastasis stage." (PMID 33853611, 2021). "The results indicate that the RP11-2C24.4 levels increased while the RP11-284N8.3, RP11-399O19.9, LINC00641, and MAGI2-AS3 levels decreased in the tumor tissues." (PMID 30984308, 2019). "In addition, LINC00641 was downregulated in patients with NSCLC and exerted tumor-suppressive role by suppressing cell proliferation and inducing cell apoptosis through sponging miR-424-5p." (PMID 33853611, 2021). "However, LINC00641 was localized primarily in the nucleus, suggesting the tumor-suppression effect of LINC00641 was not entirely dependent on the ceRNA regulatory network in the cytoplasm." (PMID 37311754, 2023).
cancer (9 papers, 2020 to 2023). A tumor composed of atypical neoplastic, often pleomorphic cells that invade other tissues. "LINC00641 has been reported to exert various biological functions in several cancers by acting as a competitive endogenous RNA (ceRNA)." (PMID 37311754, 2023). "In this review, the biological functions, related mechanisms and clinical significance of LINC00641 in many human cancers are described in detail." (PMID 35155216, 2021). "The mechanism of LINC00641 in cancer has been concentrated in recent 5 years, which can be used as an emerging biomarker of cancer prognosis." (PMID 35155216, 2021). "LINC00641 has been reported to be involved in the initiation and development of several cancers in the recent years." (PMID 33853611, 2021). "In this paper, we elaborate the biological function, related mechanism and clinical significance of LINC00641 in human cancer." (PMID 35155216, 2021). "Furthermore, we illustrated the expression of pyroptosis immune regulators across another∼10000 samples and revealed that CNST, GDF10, KCNC2, NAP1L2, NCOA7, and LINC00641 also revealed higher expression in cancer cells." (PMID 35620284, 2022). "Linc00641 plays different roles in various types of human cancers." (PMID 33714199, 2021). "Several studies have revealed an antitumor role of linc00641 in human cancers." (PMID 33714199, 2021). "Linc00641 has been reported to mediate cell apoptosis in cancer cells." (PMID 33714199, 2021). "Several reports have demonstrated that linc00641 affects migration and invasion of cancer cells." (PMID 33714199, 2021). "Therefore, more studies are required to investigate the biological functions and molecular mechanisms of LINC00641 in a variety of cancers." (PMID 32917936, 2020).